MMP8 (matrix metallopeptidase 8)
Diseases named in the same sentence as MMP8 in open-access papers (continued):
Sharing a sentence is not in itself a finding about the gene and the disease.
Granuloma (2 papers, 2017 to 2024). A compact, organized collection of mature mononuclear phagocytes, which may be but is not necessarily accompanied by accessory features such as necrosis. "Five traits: lung granuloma necrosis (“Necr Ratio”), weight loss, MMP8, CXCL1, and IL-10 mapped to Dots8." (PMID 38861581, 2024).
injury (2 papers, 2014 to 2025). Damage inflicted on the body as the direct or indirect result of an external force, with or without disruption of structural continuity. "One study demonstrated that higher concentrations of MMP-8 in amniotic fluid were significantly associated with an increased risk of CP by age 3, supporting the hypothesis that increased extracellular matrix remodeling during pregnancy may predispose to perinatal brain injury." (PMID 41464177, 2025). "Furthermore, MMP-8 has protective anti-inflammatory activities in mice with acute lung injury and allergen-induced airway inflammation, but pro-inflammatory activities during acute hepatic injury in mice." (PMID 24828408, 2014).
joint diseases (2 papers, 2013 to 2015). "Muscle and joint diseases were associated with increased IL-1β, MMP-8 and the ratio MMP-8/TIMP-1." (PMID 23637817, 2013). "The levels of IL-1β, IL-8 and MMP-8, as well as the MMP-8/TIMP-1 ratio were higher in subjects with muscle and joint diseases." (PMID 23637817, 2013).
juvenile idiopathic arthritis (2 papers, 2019 to 2022). Juvenile idiopathic arthritis (JIA) is the term used to describe a group of inflammatory articular disorders of unknown cause that begin before the age of 16 and last over 6 weeks. "The aim of this study was to evaluate the concentration of MMP-2, MMP-8, and MMP-9 and their inhibitors TIMP-1 and TIMP-2 of unstimulated whole saliva (UWS) in correlation with the oral health in juvenile idiopathic arthritis (JIA) children." (PMID 31781639, 2019).
juvenile periodontitis (2 papers, 2020). "TIMP levels were shown decreased, enhanced, or unaltered in adult/juvenile periodontitis and after periodontal therapy; while MMP-8, on the other hand, represented a consistently-promising periodontal biomarker itself." (PMID 33143325, 2020).
kidney cancer (2 papers, 2019 to 2025). Primary or metastatic malignant neoplasm involving the kidney. "On the other hand, several studies show that some cancer treatments may also increase MMP8 levels: Increased expression of proangiogenic factors, including MMP8, by myeloid derived suppressor cells could contribute to resistance to Sunitinib treatment seen in some kidney cancer patients." (PMID 31514474, 2019).
leukocytosis (2 papers, 2013 to 2020). "The additional impulse for MMP-8 release may be the direct blood-membrane contact with subsequent transient leukocytosis during hemodialysis sessions, explaining the difference between HD and APD patients." (PMID 23054081, 2013).
lung adenocarcinoma (2 papers, 2019 to 2021). A carcinoma that arises from the lung and is characterized by the presence of malignant glandular epithelial cells. "Lung adenocarcinoma cells treated with hepatocyte growth factor variants showed inhibition of proliferation, reduced invasion and increased amounts of active MMP8, which was suggested to facilitate the tumor-protective effects." (PMID 31514474, 2019). "Nevertheless, there are limited data regarding the direct effect of MMP8 molecule on the cellular behaviour of lung adenocarcinoma cells." (PMID 34356991, 2021). "In another study, treatment with hepatocyte growth factor could upregulate the expression of MMP8 in lung adenocarcinoma cells, which in turn, enhanced the intercellular adhesion, thereby alleviating the migration activity of cells." (PMID 34356991, 2021).
lymphoma (2 papers, 2016 to 2026). A malignant (clonal) proliferation of B- lymphocytes or T- lymphocytes which involves the lymph nodes, bone marrow and/or extranodal sites. "MMP8 expression also has been reported in other lymphomas such as mantle cell lymphoma and Waldenstrom macroglobulinemia and correlates with poor prognosis and lymphoma growth." (PMID 27050077, 2016). "Lymphoma cell invasion was attenuated with an MMP8 inhibitor, implicating OPN-induced expression of this particular collagenase for the first time in lymphoma cell invasion." (PMID 27050077, 2016). "As OPN expression correlated most with MMP8 in both lymphoma cell models, we further examined the role of MMP8 in lymphoma cell invasion using a specific inhibitor of MMP8 in transwell invasion assays." (PMID 27050077, 2016). "Given this information, OPN directed MMP8 expression might be critical for highly selective CNS tropism and penetration of lymphoma cells." (PMID 27050077, 2016). "Since MMP8 functions primarily as a collagenase, we examined the effects of OPN expression on the ability of lymphoma cells to degrade collagen." (PMID 27050077, 2016). "Moreover, the NF-κB inhibitor (IKK2) similarly suppressed lymphoma cell invasiveness and collagenase activity, supporting a direct role for OPN-mediated activation of NF-κB in MMP8 regulation, extracellular matrix (ECM) remodeling, and lymphoma cell invasion." (PMID 27050077, 2016).
malignant thyroid neoplasms (2 papers, 2013 to 2019). "MMP8 mRNA was elevated in skin samples of basal cell carcinoma patients compared to healthy controls and in malignant thyroid neoplasms compared to benign neoplasms." (PMID 31514474, 2019). "The MMP27 gene was analyzed for mutation in ATC in the present study as we had already previously analyzed the second gene, MMP8, in thyroid cancer." (PMID 24137342, 2013). "Serum MMP8 levels did not correlate with the presence of tumors in thyroid cancer patients." (PMID 31514474, 2019).
meningococcal infection (2 papers, 2010 to 2023). Infections with bacteria of the species neisseria meningitidis. "Together, we established that MMP-8 activity plays a crucial role in disassembly of cell junction components and cell adhesion during meningococcal infection." (PMID 20442866, 2010). "Taken together our data support the central role of MMP-8 in the disassembly of both host cell junction components and cell adhesion to the ECM as a consequence of meningococcal infections." (PMID 20442866, 2010).
multiple myeloma (2 papers, 2018 to 2019). "Bone marrow cells produce MMP8 along with other MMPs during multiple myeloma progression in vivo and the tumor growth can be reduced with the broad spectrum MMP inhibitor; SC-964." (PMID 31514474, 2019).
myocarditis (2 papers, 2021 to 2022). Myocarditis is a condition that is characterized by inflammation of the heart muscle (myocardium). "The studies on sex-driven MMP expression in myocarditis are preliminary, and the only work we found in mice observed an increase in MMP-8 expression in the heart during myocarditis." (PMID 35893290, 2022). "The transcription of many MMPs, especially MMP-3, MMP-8 and MMP-9 are upregulated in the acute phase of CVB3-induced myocarditis." (PMID 34452454, 2021).
nasal polyp (2 papers, 2021 to 2024). "Previous studies provided evidence for higher levels of MMP‐1, MMP‐2, MMP‐3, MMP‐7, MMP‐8, and MMP‐9 in nasal polyps." (PMID 34504680, 2021).
oral mucositis (2 papers, 2019 to 2026). Inflammation of the mucous membranes of any of the structures in the mouth. "MMP8 levels in some body fluids can also be used to assess post-operative reactions: HNSCC patients, who developed radiochemotherapy-induced oral mucositis, had a higher salivary MMP8 level than those who did not develop this reaction." (PMID 31514474, 2019).
oral squamous cell carcinoma (2 papers, 2015 to 2019). "This present study was carried out to examine the immunohistochemical expression of MMP-2 and MMP-8 in oral squamous cell carcinoma cases seen at the Department of Oral Pathology, University College Hospital Ibadan." (PMID 26155333, 2015). "MMP8 is abundant in oral squamous cell carcinoma (OSCC) tumors, but the higher level does not correlate with clinicopathological features nor does it increase the survival of the patients." (PMID 31514474, 2019). "Key words:Oral squamous cell carcinoma, MMP-2, MMP-8, immunohistochemistry." (PMID 26155333, 2015).
Ovarian cyst (2 papers, 2019 to 2024). The presence of one or more cysts of the ovary. "In the fluid of ovarian cysts, elevated levels of MMP8 was associated with tumor malignancy." (PMID 31514474, 2019). "In contrast to MMP-8, the activity of this enzyme in fluid collected from malignant and non-malignant ovarian cysts is low and does not differ between groups." (PMID 39682156, 2024).
pancreatic adenocarcinoma (2 papers, 2019 to 2023). "Pancreatic adenocarcinomas showed higher MMP8 levels compared to normal tissue, especially in patients with short survival time." (PMID 31514474, 2019). "As an example, intact COLα1 (I) was shown to promote DDR1 degradation in a mouse pancreatic adenocarcinoma cell line, whereas a COLα1 (I) fragment (from the N-terminus until and including Gly775) produced following MMP-8 cleavage, was found to activate the DDR receptor." (PMID 37373151, 2023).
pancreatic ductal adenocarcinoma (2 papers, 2019 to 2022). An infiltrating adenocarcinoma that arises from the epithelial cells of the pancreas. "MMP8 levels in blood decreased after tumor removal in paraganglioma and pancreatic ductal adenocarcinoma patients." (PMID 31514474, 2019).
polycystic ovarian syndrome (2 papers, 2022 to 2023). "For instance increased levels of MMP-8 and the MMP-8: TIMP-1 ratio in saliva and serum seem to be more pronounced in women with polycystic ovarian syndrome and they are potentiated by gingival inflammation." (PMID 36012195, 2022).
pulmonary arterial hypertension (2 papers, 2024). Pulmonary arterial hypertension (PAH) is a group of diseases characterized by mean pulmonary artery pressure >20 mmHg and elevated pulmonary arterial resistance leading to right heart failure. "Drawing on pulmonary arterial hypertension (PAH) as an illustrative example, extensive documentation exists regarding the interaction between β3 integrins on the cell membrane of pulmonary artery smooth muscle cells (PASMCs) and MMP8, which is secreted by PASMCs." (PMID 38612904, 2024).
rectal cancer (2 papers, 2019 to 2023). A primary or metastatic malignant neoplasm that affects the rectum. "Elevated MMP8 levels in intraperitoneal fluid were also seen in rectal cancer patients who developed anastomotic leakage after surgery." (PMID 31514474, 2019). "Moreover, MMP8 rs3740938 was related to the pathological type of rectal cancer." (PMID 38031100, 2023).
skin papilloma (2 papers, 2015 to 2016). A benign papillary neoplastic growth on the skin composed of epithelial cells and a fibrous stalk. "Male Mmp8-null mice have been shown to have enhanced formation of skin papillomas, which could be rescued by transfer of bone marrow from wild-type mice, suggesting that neutrophils (as the main source of MMP-8) are protective in the early stages of lesion formation." (PMID 25848906, 2015).
viral infection (2 papers, 2024 to 2026). "This research explores the structural and functional consequences of high-impact missense variants in three immune-related genes MMP8 (D253N, Y261S), GZMK (A42P, L122P), and OASL (W216C) with possible relevance to host response in epidemic viral infections." (PMID 41807577, 2026). "MMP-8 is among the top 5 biomarkers for distinguishing bacterial peritonitis from sterile peritoneal inflammation or viral infection." (PMID 38893639, 2024).
abscesses (1 paper, 2016). "The high lesional MMP8 levels were accompanied by elevated blood levels that positively correlated with TNF-α blood levels and disease severity assessed by Sartorius score, especially with the number of regions with inflammatory nodules/abscesses and fistulas." (PMID 27843200, 2016).
acute pancreatitis (1 paper, 2013). An acute inflammatory process that leads to necrosis of the pancreatic parenchyma. "This is in line with the notion that MMP8 and MMP9 are expressed by neutrophils and with previous reports that plasma MMP9 is increased in acute pancreatitis." (PMID 23442769, 2013).
acute pyelonephritis (1 paper, 2019). "In the present study, we have examined the mRNA levels of IL-6, MMP-8 and GSS using saliva as an emerging, non-invasive and perspective medium for precise diagnosis of acute pyelonephritis in children." (PMID 31881666, 2019).
adrenal tumors (1 paper, 2021). "In addition, the MMP-9 and MMP-8 serum levels were evaluated in patients with adrenal tumors prior and after surgery." (PMID 35201460, 2021).
adrenocortical tumor (1 paper, 2021). "Together, we showed that MMP-8 and MMP-9 play an important role in adrenocortical tumor cell motility, which may suggest a role in the metastatic process." (PMID 35201460, 2021).
airway hyperresponsiveness (1 paper, 2025). "Mmp8 contributed to airway hyperresponsiveness and remodeling by altering extracellular matrix turnover, affecting smooth muscle contraction and airway fibroblast invasion." (PMID 40313552, 2025).
ameloblastoma (1 paper, 2021). The most common odontogenic tumor, arising from the epithelial component of the embryonic tooth and usually affecting the molar-ramus region of the mandible or maxilla. "Polymorphonuclear neutrophils and plasma cells showed MMP‐8 immunopositivity but ameloblastoma cells were negative." (PMID 32985799, 2021). "Neither MMP‐8 nor MMP‐9 immunoexpression could be detected in ameloblastoma cells." (PMID 32985799, 2021).
aneurysmal disease (1 paper, 2022). "In addition to its well-proved antimicrobial capabilities, doxycycline inhibits phorbol-12-myristate-13-acetate-mediated matrix metalloproteinase 8 (MMP-8) and MMP-9 in human endothelial cells, reducing elastin degradation and MMP activity in a model of aneurysmal disease." (PMID 35808704, 2022).
ankylosis (1 paper, 2021). Fixation and immobility of a joint. "Nevertheless, EMD can be stressful for the root surface, during the resorption process of the gel matrix an inflammatory process can be activated due to the degradation with the activation of MMP8 and the resorption of the root surface or more complicated ankylosis." (PMID 34684108, 2021).
Anxiety (1 paper, 2026). Intense feelings of nervousness, tension, or panic often arise in response to interpersonal stresses. "Greater increases in circulating MMP-8 were associated with greater worsening of GHQ scores, driven primarily by the Anxiety/Insomnia subscale." (PMID 42094850, 2026).
aortic stenosis (1 paper, 2017). Aortic valve stenosis is a aortic valve disease caused by the incomplete opening of the aortic valve. "For example, MMP-2 and MMP-14 levels robustly increase in LV pressure overload models and myocardial biopsies of aortic stenosis (AS), whereas the levels of MMP-14, MMP-7, MMP-8, and MMP-9 increase in end-stage dilated cardiomyopathy." (PMID 28484397, 2017).
aortic valve diseases (1 paper, 2012). "The BAV group with a combination of aortic valve diseases had significantly increased MMP-8 and MMP-9 levels in the convex aortic sites." (PMID 22645456, 2012).
arterial disease (1 paper, 2019). "Moreover, the AA genotype of rs1122539 was significantly associated with increased MMP-8 serum levels and the A allele of rs1122539 was associated with an increased risk of arterial disease." (PMID 31067818, 2019).
Ascites (1 paper, 2010). Accumulation of fluid in the peritoneal cavity (between the layers of the peritoneum that lines the abdomen). "All cirrhotic animals injected with Ad-huPA plus Ad-MMP8 showed moderate ascites." (PMID 20509929, 2010).
autism (1 paper, 2022). Persistent deficits in social interaction and communication and interaction as well as a markedly restricted repertoire of activity and interest as well as repetitive patterns of behavior. "Overall, the literature on the ITGB3BP, DDR1, and MMP8 genes indicates that the observation regarding the integration of transcriptome and exome genotyping in autism is a notable addition for the understanding of the genetics of autism." (PMID 35215271, 2022). "The fivefold downregulated MPO, TMCC3, MMP8, CA1, and ELF3 genes and the fivefold upregulated MTRNR2L8 gene can be considered for the early identification of autism patients among Saudis." (PMID 35215271, 2022).
autism spectrum disorder (1 paper, 2022). A spectrum of developmental disorders that includes autism, and Asperger syndrome. "Regulatory variations (rs6657480, rs3130780, and rs1940475) identified the up- (ITGB3BP) and downregulation (DDR1 and MMP8) of genes in autism spectrum disorder in patients of Arab ancestry discovered through the integration of up- and downregulated genes and genes of significant genotypes." (PMID 35215271, 2022). "The integration of significantly up- and downregulated genes and genes of significant SNPs identified regulatory variants (rs6657480, rs3130780, and rs1940475) associated with the up- (ITGB3BP) and downregulation (DDR1 and MMP8) of genes in autism spectrum disorder in people of Arab ancestries." (PMID 35215271, 2022).
autoimmune disease (1 paper, 2022). A disorder resulting from loss of function or tissue destruction of an organ or multiple organs, arising from humoral or cellular immune responses of the individual to their own tissue constituents. "Just like MMP-8, MMP-9 is another important enzyme that plays a part in multiple autoimmune diseases." (PMID 36221125, 2022).
autoimmune myocarditis (1 paper, 2022). Autoimmune myocarditis is an autoimmune disease that affects the heart. "In addition, MMP8 has been found to be differentially changed in the urine of individuals with autoimmune inflammatory diseases, such as experimental autoimmune myocarditis." (PMID 35274006, 2022).
bladder tumors (1 paper, 2019). "In bladder tumors, MMP8 mRNA expression was not strong enough to show significant correlation to malignancy." (PMID 31514474, 2019).
bone metabolism disorders (1 paper, 2025). "Matrix metalloproteinase 8 (MMP-8) and osteoprotegerin (OPG) are considered the best-known indicators of bone metabolic disorders." (PMID 40363983, 2025). "Thus, MMP-8 and OPG are promising for diagnosing the early stages of bone metabolism disorders in children with CKD and can be considered predictive and prognostic markers." (PMID 40363983, 2025).
bone mineral disorders (1 paper, 2025). "The results of our study show the possibility of using MMP-8 and OPG in saliva to detect the initial stages of the development of periodontal inflammatory changes and bone mineral disorders in children with different stages of CKD." (PMID 40363983, 2025).
brain tumors (1 paper, 2024). "The role of MMP8 in brain tumors is poorly understood to date." (PMID 38474106, 2024).
Campylobacter enteritis (1 paper, 2018). "In conclusion, after human Campylobacter enteritis, the serum levels of MMP-8, MMP-9 and their regulators MPO, HNE and TIMP-1 are elevated as compared to the serum levels of healthy controls." (PMID 30551610, 2018).
carotid body paraganglioma (1 paper, 2019). A benign or malignant extra-adrenal parasympathetic paraganglioma arising from paraganglia adjacent to or in the bifurcation of the common carotid artery. "Similarly, higher plasma MMP8 levels were demonstrated in carotid body paraganglioma patients compared to healthy persons, but not patients with malignant disease." (PMID 31514474, 2019).
chondrosarcoma (1 paper, 2019). A malignant cartilaginous matrix-producing mesenchymal neoplasm arising from the bone and soft tissue. "In chondrosarcoma and soft tissue neoplasms, MMP8 staining was either absent or weak, and thus, no conclusions could be made of its role." (PMID 31514474, 2019).